PIM1 (Pim-1 proto-oncogene, serine/threonine kinase)
Diseases named in the same sentence as PIM1 in open-access papers (continued):
Sharing a sentence is not in itself a finding about the gene and the disease.
breast carcinoma (continued). "UM171 increased the expression of the three PIM genes (PIM1-3) in breast cancer cells." (PMID 38874684, 2024). "The protein kinases CK2 and PIM-1 are involved in cell proliferation and survival, the cell cycle, and drug resistance, and they are found overexpressed in virtually all types of human cancer, including breast cancer." (PMID 36243702, 2022). "This further supports Pim1 as a potential target in breast cancer metastasis." (PMID 34283050, 2021). "Since we observed that HER2 expression was associated with Pim1 inhibitor sensitivity, we further examine whether HER2-positive breast cancers are more sensitive to Pim1 inhibitors." (PMID 34267653, 2021). "Furthermore, in clinical data from luminal A subtype of breast cancer, PIM1 and NOTCH3 mRNA levels correlate positively." (PMID 33775697, 2021). "We confirmed in our work that RUNX3 could attenuate the stem cell–like traits in breast cancer cells and mediate the antitumour effects of PIM1 inhibition in this way." (PMID 32307917, 2020). "It was well mentioned that PIM1 played pivotal roles in the tumorigenesis of breast cancer." (PMID 32307917, 2020). "All these clinicopathological results suggested that RUNX3 dislocation may mediate the tumorigenic effects of PIM1 in breast cancer." (PMID 32307917, 2020). "Moreover, we tried to further confirm the possible role of PIM1 in the gaining of stem cell–like traits for breast cancer cells." (PMID 32307917, 2020). "All these results suggested that PIM1 could promote the EMT process of breast cancer cells and this effect could be attenuated by RUNX3 and reversed by RUNX3(4A)." (PMID 32307917, 2020). "We also firstly reported the “pro‐stemness” effects of PIM1 in breast cancer cells." (PMID 32307917, 2020). "In brief, PIM1 could enhance the stem cell–like traits of breast cancer cells by promoting the phosphorylation and cytoplasmic localization of RUNX3." (PMID 32307917, 2020). "More work needed to be conducted to interrogate whether PIM1 inhibition could suppress tumour metastasis in breast cancer." (PMID 32307917, 2020). "In conclusion, all these results suggested that PIM1 could promote breast cancer cells to gain stem cell–like traits and inhibiting PIM1 promised to exert anti‐BrCSC effects with RUNX3 being indispensable in this process." (PMID 32307917, 2020). "Taken together, our data suggested that PIM1 might be a target for IL-6 induced breast cancer cell EMT and stemness." (PMID 30989585, 2019). "We determined whether IL-6 induced PIM1 in breast cancer cell lines, leading to the increased expression of PIM1." (PMID 30989585, 2019). "This study proposed the upregulation of PIM1 by IL-6 contributed to breast cancer cell aggressiveness and targeting PIM1 or c-myc could be novel approaches for breast cancer treatment." (PMID 30989585, 2019). "Previous reported implied that IL-6 might link with the expression of PIM1 in pancreatic cancer cells and fibroblasts, and we observed this regulation pattern in breast cancer as well." (PMID 30989585, 2019). "Hence, our data for the first time, indicated that PIM1 was a downstream target of IL-6 and critical for breast cancer cell EMT and stemness." (PMID 30989585, 2019). "Previous evidence has shown that overexpression of PIM1 in various human cancers, such as breast cancer, mesothelioma and glioblastoma, is well correlated with the processes of cancer progression, including cell proliferation, cell cycle arrest, apoptosis, migration, invasion and drug resistance." (PMID 29472550, 2018). "However, in human breast cancer cells, PIM-1 is regulated by estrogen signaling, and its expression level contributes to the growth of mammary carcinoma cells." (PMID 28938604, 2017). "However, PIM1 transgenic mice also exhibited a clear percentage of females with macroscopic mammary tumors." (PMID 28938604, 2017).
breast carcinoma (continued). "However in breast cancer, whether PIM1 acts as an upstream regulator of RUNX3 to phosphorylate it and promote its subcellular dislocation remains unclear and whether this mechanism plays a part in BrCSC‐regulating effect of RUNX3 is hardly referred before." (PMID 32307917, 2020). "As expected, facilitating PIM1 expression in breast cancer cells (MCF‐7, T47D, MDA‐MB‐231 and BT‐549) led to elevated mammospheres formation capacity and that was reduced by additionally overexpression of RUNX(4A)‐FLAG, which is deficient of the phosphorylation sites targeted by PIM1." (PMID 32307917, 2020). "Interestingly, the invasion capacity of breast cancer cells was also reduced by knocking down PIM1 and the anti‐invasion effect of siPIM1 could also be attenuated by additionally knocking down RUNX3." (PMID 32307917, 2020). "Thus, PIM1 is critical in promoting breast cancer cell EMT and stemness." (PMID 30989585, 2019). "However, it is still elusive about the role of PIM1 in breast cancer." (PMID 30989585, 2019). "Hence, PIM1 acted as a potential target for breast cancer therapy." (PMID 30989585, 2019). "Collectively, we noticed that IL-6 could enhance the expression of PIM1 in breast cancer cells." (PMID 30989585, 2019). "Moreover, we determined the biological functions of PIM1 in breast cancer, not only the growth but the metastasis and stemness, and supported the rationale that inhibition of PIM1 and c-myc could have clinical benefit for breast cancer patients." (PMID 30989585, 2019). "Furthermore, a recent study found that PIM1 is upregulated in breast cancer cells that are resistant to the PI3K inhibitor BYL719 and that all three PIM kinases are capable of sustaining mTORC1 signaling and cell proliferation in the presence of the inhibitor in these resistant cells." (PMID 29170467, 2017). "Given that previous studies showed that breast cancer, as well as leukemic cells, is sensitive to dual CK2/PIM-1 inhibitor treatment, two leukemic cell lines, i.e., CCRF-CEM and K-562, and breast cancer cells, i.e., MCF-7, were used in the present study." (PMID 37514177, 2023). "Its ability to induce apoptosis in breast cancer cells can be attributed to efficient intracellular inhibition of both CK2 and PIM-1 activity." (PMID 37514177, 2023). "In prostate and lung malignancies, acute myeloid leukemia, pancreatic ductal adenocarcinoma, and breast cancer, overexpression of the kinases CK2 and PIM-1 in patient tumors correlates with poor prognosis and is regarded an unfavorable prognostic marker." (PMID 36243702, 2022). "In various breast cancer cell lines, intrinsic resistance to the PI3Kα or AKT inhibitors has been demonstrated to involve PIM1, with PIM3 likely playing a less prominent role in this setting." (PMID 35440108, 2022). "This was supported by the micromolar/submicromolar affinity of quercetin towards proto-oncogene serine/threonine–protein kinase (PIM-1) and hematopoietic cell kinase (HCK), both involved in breast cancer." (PMID 33946222, 2021). "It is interesting that quercetin was predicted to interact with PIM-1 and HCK proteins involved in breast cancer." (PMID 33946222, 2021). "The IL-6/STAT3 signaling cascade modulates PIM1, a proto-oncogene that induces cell invasion and upregulates the expression of EMT in breast cancer." (PMID 34488773, 2021). "Our results also demonstrated that Pim1 regulates protein expression of the HER family in breast cancer cells, indicating that a common upregulation of the HER family by Pim-1 in various cancer types." (PMID 34267653, 2021). "Altogether, our results provide a feasible explanation for the functional similarities of MYC, PIM1, and PML in TNBC and encourage further study of PML targeting strategies for the treatment of this breast cancer subtype." (PMID 31570853, 2020). "Next, we sought to further clarify the expression pattern of PIM1 and RUNX3 in breast cancer tissues." (PMID 32307917, 2020).
breast carcinoma (continued). "This association was evident in two out of four datasets for MYC-PML and four out of four for PIM1-PML, when accounting all breast cancer subtypes." (PMID 31570853, 2020). "Inhibition of PIM1 significantly induced the nuclear retention of RUNX3, recovered its transcriptional function and attenuated the stem cell–like properties of breast cancer cells." (PMID 32307917, 2020). "In the present study, we indicated that PIM1 was transcriptional activated by IL-6/STAT3 axis and was critical for IL-6 induced breast cancer cell EMT and stemness." (PMID 30989585, 2019). "In summary, our findings provided insight into the mechanism by which pro-inflammatory cytokine IL-6 induced breast cancer cell EMT and stemness and provided the potential approach to suppress the upregulation of PIM1 by IL-6." (PMID 30989585, 2019). "In the present study, our data identified that PIM1 was induced by IL-6 and participated in IL-6-mediated EMT and stemness in breast cancer." (PMID 30989585, 2019). "Breast cancer cell lines T47D and MCF7 were exposed to IL-6, the expression of PIM1 was examined by quantitative real-time PCR (qRT-PCR) and western blot." (PMID 30989585, 2019). "This notion is clear given that 19% of PIM1 Tg female and a 7% of PIM2 Tg female harbored mammary tumors." (PMID 28938604, 2017). "These analyses revealed positive Pearson correlations between PIM1 and NOTCH1 in both types of cancer as well as between PIM1 and NOTCH3 in breast cancer." (PMID 27281612, 2016). "Our research re-evaluates the carcinogenic risks of plastic stabilizers and suggests that PSs may enhance breast cancer progression via targets such as MAPK14, PIM1, and TRDMT1." (PMID 41790613, 2026). "Furthermore, this phosphorylation enhances the tumorigenic behavior of both breast and prostate cancer cells, as also suggested by the observed coexpression of PIM1 and NOTCH1 mRNAs in patients with breast cancer." (PMID 33775697, 2021). "In conclusion, our study indicates that downregulation of HER2 by targeting Pim1 may be a promising and effective therapeutic approach for HER2-positive breast cancer cells and for circumventing lapatinib resistance." (PMID 34267653, 2021). "We find that Pim1, MAPKAPK2, and CK2 are kinases that are activated on the lung FDM, and were inhibited on the lung ECM alone, which would be good candidates to investigate when looking at breast cancer metastasis to the lungs." (PMID 34283050, 2021). "The tumoral Pim1 mRNA expression was higher in lapatinib-treated patients with HER2-positive breast cancers than in the patients without lapatinib treatment in a published gene set (GSE130788)." (PMID 34267653, 2021). "In order to investigate whether HER2 acts as a determinant for the sensitivity to Pim1 inhibitors, HER2 was overexpressed in different breast cancer cells followed by measuring their sensitivity to SMI-4a." (PMID 34267653, 2021). "And this implied us that PIM1 might exert both its pro‐BrCSC and pro‐EMT effects by phosphorylating RUNX3 due to the fact that breast cancer cells could gain stem cell–like traits by undergoing EMT process." (PMID 32307917, 2020). "We thus sought to investigate the role of PIM1 and RUNX3 in EMT process of breast cancer cells." (PMID 32307917, 2020). "We demonstrated that PIM1 could phosphorylate RUNX3 to facilitate its cytoplasmic retention, thus suppressing the transcriptional activity of RUNX3 and promoting breast cancer to gain BrCSC‐like traits." (PMID 32307917, 2020). "Besides, PIM1 was shown by our results to co‐localize with and directly bind with RUNX3 in cytoplasm of breast cancer cells." (PMID 32307917, 2020). "Previous studies have implied that MYC was a target of PIM1 and PIM1 inhibition abrogated the growth of MYC-overexpressing tumors, we detected whether MYC was involved in PIM1-induced breast cancer EMT and stemness." (PMID 30989585, 2019).
breast carcinoma (continued). "PIM1 mRNA level was explored using quantitative PCR and we found that IL-6 could significantly elevate the mRNA of PIM1 in T47D and MCF7 breast cancer cells." (PMID 30989585, 2019). "Of note, inhibition of the AKT has been shown to upregulate the PIM1, which may confer resistance to PI3K inhibitor therapy in breast cancer." (PMID 29927999, 2018). "Screening a panel of ovarian cancer cell lines that included ES2, OVCA194, OVCAR4, OVCAR3, and OVCA420 showed that all of the ovarian lines expressed the 33 kDa form of PIM1, while the breast cancer cell lines, MCF-7, MCF-10A, MDA-MB-231 and MDA-MB-435 expressed the 44 kDa isoform of PIM1." (PMID 28090373, 2016). "However, the possibility that other downstream effectors of Pim1 mediate the anti-cancer activity of Pim1 inhibitor in HER2-positive breast cancer cells can not be excluded." (PMID 34267653, 2021). "However, the in‐depth oncogenic mechanism of PIM1 is not well‐elucidated, especially concerning its effect on breast cancer stem cells (BrCSCs)." (PMID 32307917, 2020). "And in this paper, we revealed PIM1 to be promising for targeting at to wipe out CSC population specifically due to its regulation on RUNX3 cytoplasmic translocation, and inhibition of PIM1 could attenuate stem cell–like traits of breast cancer cells." (PMID 32307917, 2020). "PIM‐1 can inhibit the growth of triple‐negative breast cancer cells, so the decrease of PIM1 expression caused by HN1L gene silencing may be one of the ways by which HN1L regulates the proliferation of breast cancer cells." (PMID 33191617, 2021). "However, we found that PIM1 induced breast cancer cell EMT and stemness, which might be independent of the hormone status." (PMID 30989585, 2019). "No major differences were detected between PIM1 and NOTCH3 mRNA expression levels in different breast cancer stages, whereas the PIM1 levels were reduced in most subtypes as compared with control samples." (PMID 33775697, 2021). "As expected, PIM1 was pervasively expressed across breast cancer cell lines irrespective of hormone receptor status with the exception of MCF‐10A, a normal human breast epithelial cell line, which barely expressed PIM1." (PMID 32307917, 2020). "In summary, downregulation of HER2 by targeting Pim1 may be a promising and effective therapeutic approach not only for anti-cancer growth but also for circumventing lapatinib resistance in HER2-positive breast cancer patients." (PMID 34267653, 2021).
leukemia (30 papers, 2006 to 2026). A malignant (clonal) hematologic disorder, involving hematopoietic stem cells and characterized by the presence of primitive or atypical myeloid or lymphoid cells in the bone marrow and the blood. "PIM1 overexpression is linked to poor clinical outcomes in patients with leukemia and triple-negative breast cancer." (PMID 38339286, 2024). "Although both factors regulate PIM1 expression, the FLT3-ITD axis is more sensitive and is responsible for PIM1 downregulation with low-dose DOT1L inhibitor treatment in MLL-r leukemia also bearing the FLT3-ITD mutation." (PMID 34263728, 2021). "PIM2 and PIM3 did not appear to be correlated with ABC protein expression, although these studies focused on leukemia and myeloma, in which PIM1 is known to play a larger role." (PMID 33727604, 2021). "STAT5 induces the expression of its target genes, such as, cyclin D1, c-myc and the protooncogene Pim-1, which mediates the proliferative and antiapoptotic behavior of leukemia cells via the FLT3-ITD signaling pathway." (PMID 31434952, 2019). "Herein we reported the role and the molecular mechanisms of Pim1 in regulating c-Kit expression in murine HSPCs and in human leukemia cells." (PMID 28042518, 2016). "Some of these genes have been previously found to play important roles in haematopoiesis and leukaemia pathogenesis, e.g. PIM1, BCOR, TNFRSF8 and NR4A2." (PMID 26576536, 2015). "The serine/threonine-protein kinase Pim-1 is upregulated in a number of hematological malignancies such as leukemia, mantle-cell lymphoma, and diffuse large B-cell lymphoma (DLBCL)." (PMID 25121590, 2014). "The oncogene Pim1 was found rearranged in Friend helper MuLV-induced erythroleukaemias and Graffi-induced leukaemias." (PMID 20102610, 2010). "As part of our laboratory drug discovery program aimed at identifying new targeted therapies for the treatment of hematologic malignancies, and, regarding the particular potential of Pim-1 and Pim-2 as targets in leukemia, we decided to develop new dual Pim-1/Pim-2 specific inhibitors." (PMID 33562106, 2021). "We compared the protein expression level of p-STAT5/STAT5, Pim-1 and CXCR4 among the FLT3-ITD-mutated, FLT3-wt and normal control groups using Western blotting to further examine whether CXCR4 expression in leukemia cells is regulated by FLT3-ITD mutations." (PMID 31434952, 2019). "We propose that UM171 exerts its effect through two independent pathways (i) HSC expansion markers via PIM1, which could increase leukemia stemness; (ii) growth suppression via as yet to be defined target that controls the tumor suppressor genes KLF2 and P21CIP1." (PMID 36335089, 2022). "Pim-1 was highly expressed in complex AML, CLL, ALL, and MDS, while Pim-2 was especially prevalent in CML compared to other leukemias." (PMID 36694243, 2023). "PIM1 facilitates the proliferation and inhibits apoptosis of AML cells, but also enhances the chemotactic ability of leukemia cells." (PMID 36479666, 2023). "The PIM proteins are a family of 3 protooncogene serine/tyrosine kinases (PIM1-3) that are upregulated in, and indicative of poor prognosis in leukemia, prostate, mesothelioma and other cancers." (PMID 34263728, 2021). "Functional analyses conducted in mice and human CD34 normal and leukemic cells have demonstrated the role of ERG in the induction of early myeloid progenitors in leukemia stem cell through the activation of RAS pathway and Pim1." (PMID 30303964, 2018). "In data published previously by us and another group, it was demonstrated that the inhibitor of protein kinases CK2 and PIM-1, 1-(β-D-2′-deoxyribofuranosyl)-4,5,6,7-tetrabromo-1H-benzimidazole (K164, also termed TDB), show anticancer activity against leukemia and cancers in vitro." (PMID 36243702, 2022).
leukemia (continued). "Taken together, low dose MLL1 and DOT1L inhibitors downregulate different, yet partially overlapping sets of genes (with FLT3, MEF2C, and PIM1 in common), that are necessary for MLL-rearranged leukemia, consistent with the synergism arising from largely distinct pathways." (PMID 34263728, 2021). "Importantly, despite the mechanism through which NPQ-C6 circumvented IM-resistance was not explored, NPQ-C6 inhibited pYBCR-ABL1, pYSTAT5, c-MYC or PIM-1 in K562-R cells, which suggests that NPQ-coumarin conjugates might be able to circumvent resistance to TKI in BCR-ABL1+ leukemia." (PMID 30687103, 2018). "We observed a reduction in the viability of the FLT3-ITD heterozygous, non-MLL-rearranged leukemia cell line PL-21 after treatment with 10 μM pinometostat for 9 days, accompanied by a reduction in both FLT3 and PIM1 expression." (PMID 34263728, 2021).